RNPEPL1 (arginyl aminopeptidase like 1)
Description:
Broad specificity aminopeptidase which preferentially hydrolyzes an N-terminal methionine, citrulline or glutamine.
Tractability: Small molecule: a drug acting on it is in phase 2 or 3 trials. PROTAC: ubiquitination databases record sites on it.
Gene: Protein-coding gene on chromosome 2 (240,565,804 to 240,581,372, forward strand). Ensembl gene ENSG00000142327.
Subcellular location (Human Protein Atlas): Nucleoplasm; Nuclear bodies
Gene Ontology:
Molecular function: initiator methionyl aminopeptidase activity; metalloaminopeptidase activity; metallopeptidase activity; zinc ion binding
Biological process: proteolysis
Genetic constraint (gnomAD): Loss-of-function variants: 46 observed, 65.06 expected, observed/expected ratio (o/e) 0.71, 90% interval 0.56 to 0.9. The synonymous counts are far from expectation, so gnomAD's model fits this gene poorly and the ratio says little. Missense variants: 869 observed, 899.28 expected, observed/expected ratio (o/e) 0.97, 90% interval 0.91 to 1.02. Synonymous variants: 525 observed, 420.02 expected, observed/expected ratio (o/e) 1.25, 90% interval 1.16 to 1.34.
Homologues: Orthologues: chimpanzee RNPEPL1 (99% identical), macaque RNPEPL1 (99% identical), dog RNPEPL1 (93% identical), rat Rnpepl1 (93% identical), mouse Rnpepl1 (93% identical), guinea pig RNPEPL1 (88% identical), tropical clawed frog rnpepl1 (64% identical), pig RNPEPL1 (61% identical), zebrafish rnpepl1 (61% identical), Caenorhabditis elegans anp-1 (16% identical), Drosophila melanogaster CG31445 (16% identical), Caenorhabditis elegans F49B2.6 (16% identical), and 11 more. Paralogues in human: RNPEP (42% identical), LTA4H (27% identical), AOPEP (22% identical), TRHDE (19% identical), ANPEP (17% identical), LVRN (17% identical), ERAP1 (17% identical), LNPEP (16% identical), ENPEP (15% identical), ERAP2 (15% identical), NPEPPS (13% identical).
Diseases named in the same sentence as RNPEPL1 in open-access papers:
RNPEPL1 is named in the same sentence as 4 diseases in open-access papers, as found by Europe PMC text mining. Sharing a sentence is not in itself a finding about the gene and the disease. The quoted sentences say what the papers report.
embryonal rhabdomyosarcoma (1 paper, 2022). A poorly circumscribed morphologic variant of rhabdomyosarcoma. "By contrast, in the LightGBM algorithm, another gene, RNPEPL1 (cg16412000), is required to be hypomethylated, and the hypermethylation of this RNPEPL1 can be further used as a criterion for the decision rule of embryonal rhabdomyosarcoma." (PMID 36619306, 2022).
RNPEPL1 also shares sentences with these, for which no sentence is quoted: asthma (1 paper); cancer (1); tumor (1).